TLX1 (T cell leukemia homeobox 1)
Diseases named in the same sentence as TLX1 in open-access papers:
TLX1 is named in the same sentence as 34 diseases in open-access papers, as found by Europe PMC text mining. Sharing a sentence is not in itself a finding about the gene and the disease. The quoted sentences say what the papers report.
acute lymphoblastic leukemia (12 papers, 2009 to 2025). Leukemia with an acute onset, characterized by the presence of lymphoblasts in the bone marrow and the peripheral blood. "HOX11, also known as TLX1, is primarily associated with acute lymphoblastic leukemia (ALL), and its presence in AML is relatively rare." (PMID 40842579, 2025). "Another group of T-cell acute lymphoblastic leukemia (T-ALL)-associated oncogenes are homeobox genes and includes members of the NK-like family, TLX1/HOX11, TLX3/HOX11L2 and NKX2-5/CSX, and of the clustered homeobox genes, HOXA5, HOXA9, HOXA10 and HOXA11." (PMID 20565746, 2010). "The homeobox gene TLX1 (for T-cell leukemia homeobox 1, previously known as HOX11) is inappropriately expressed in a major subgroup of T cell acute lymphoblastic leukemia (T-ALL) where it is strongly associated with activating NOTCH1 mutations." (PMID 20618946, 2010). "Three members of the NK-like subfamily of homeobox genes (NKLs), TLX1, TLX3 and NKX2-5, are implicated in T-cell acute lymphoblastic leukemia (T-ALL)." (PMID 19835636, 2009). "The NUP214-ABL1 fusion kinase, which is frequently observed in acute lymphoblastic leukemia (ALL), has a vital function in facilitating the cooperative attachment of TLX1 and STAT5 to enhancers, thus triggering the activation of significant oncogenes such as MYC and BCL2." (PMID 39838405, 2025). "T-cell acute lymphoblastic leukemia (T-ALL) cells represent developmentally arrested T-cell progenitors, subsets of which aberrantly express homeobox genes of the NKL subclass, including TLX1, TLX3, NKX2-1, NKX2-5, NKX3-1 and MSX1." (PMID 28151996, 2017). "Although TLX1 is not normally expressed in the hematopoietic system, its inappropriate expression due to chromosomal translocations involving T cell receptor (TCR) genes is associated with about 30% of adult and approximately 8% of childhood T-cell acute lymphoblastic leukemia (T-ALL) cases." (PMID 20618946, 2010).
leukemia (12 papers, 2010 to 2023). A malignant (clonal) hematologic disorder, involving hematopoietic stem cells and characterized by the presence of primitive or atypical myeloid or lymphoid cells in the bone marrow and the blood. "TLX1 is required for organogenesis of the spleen and neuronal cell fates and is linked to leukemia." (PMID 32341755, 2020). "However, the significance of this observation for TLX1-associated leukemogenesis as well as the leukemia-specific downstream targets of TLX1 still remained elusive." (PMID 20618946, 2010). "For example, SOX15 is related to pancreatic tumors, esophagus tumors and embryonal cell carcinoma, while CXCL5 is related to laryngeal cancer and glioma and TLX1 is related to leukemia." (PMID 34691933, 2019). "Our findings that inhibition of the NOTCH and TLX1 pathways separately had modest effects on leukemia cell growth led us to consider inhibiting these pathways concurrently." (PMID 21326611, 2011). "Given the excellent track record of T–ALL mouse models, we hope that our mouse model will launch a new investigation to implicate these pathways and evaluate molecularly targeted therapy in TLX1-driven leukemia." (PMID 21326611, 2011). "We have shown that TLX1 functions as a T-cell oncogene that is active during both the induction and the maintenance phases of leukemia." (PMID 21326611, 2011). "Overall, our experiments using 9490 cells and primary T-ALL cells show that TLX1 suppression inhibits leukemia growth both in vitro and in vivo." (PMID 21326611, 2011). "Since inhibiting TLX1 has only modest effects, drugs or agents that inhibit its downstream targets will likely have modest or even weaker effects on leukemia growth." (PMID 21326611, 2011). "We conclude from these experiments that concurrent blockade of the NOTCH and TLX1 pathways may inhibit leukemia cell growth cooperatively." (PMID 21326611, 2011). "Given the weak dependence of TLX1-initiated leukemia on TLX1, we agree that defining the downstream targets regulated by TLX1 may serve more academic than practical purpose." (PMID 21326611, 2011). "Suppression of TLX1 in vivo also transiently delayed leukemia progression." (PMID 21326611, 2011). "Our experiments with 9490 cells suggested that TLX1 inhibition can reduce leukemia growth." (PMID 21326611, 2011). "To this aim, we injected PD-TALL8 (TLX1) in NOD/SCID mice (n=8/9 mice per group), and when mice developed full-blown leukemia (as defined above), they were treated for 5 consecutive days with Givinostat or vehicle." (PMID 26764573, 2016). "TLX1, a key member of the HOX gene family, was first identified in the T-lineage leukemia cells." (PMID 34238116, 2021). "In an established T-ALL, inhibition of this function of TLX1 would presumably not affect leukemia survival." (PMID 21326611, 2011). "To rule out the possibility that nonspecific effects of doxycycline inhibit leukemia growth, we tested the effects of doxycycline on 9490 cells that retrovirally expressed TLX1." (PMID 21326611, 2011). "While BMP-like leukemias harbored fusion products known to drive high HOXA cluster expression, including MLLT10, KMT2A, NUP214, and direct HOXA::TCR fusions, T-specified leukemias had fusions to ZFP36L2 (involved in cell cycle control during T-cell beta selection) and TLX1/3." (PMID 37961674, 2023).
T-cell acute lymphoblastic leukemia (11 papers, 2009 to 2024). Acute lymphoblastic leukemia of T-cell origin. "Activation of TLX1 through either chromosomal relocation or promoter CpG island demethylation is associated with T-cell acute leukaemia." (PMID 28351398, 2017). "For example, we confirmed that the transcription factors TLX1 and TLX3 were associated with T-cell acute lymphoblastic leukemia, in line with previous reports." (PMID 38769532, 2024). "TLX is a an oncogene and its expression defines a distinct subgroup of T cell acute lymphoblastic leukemia, being TLX1+ tumors prone to aneuploidy and showing marked defects in the activation of normal mitotic checkpoints." (PMID 29228706, 2017). "Although analysis of TLX1/TLX3-induced T-cell acute lymphoblastic leukemia suggests AML1 is an oncosuppressor, overexpression of wt.AML1 promotes the development of mouse T-cell lymphoma and accelerates leukemogenesis in BXH2 mice." (PMID 24098673, 2013). "Notably, we have reaffirmed the well-established associations between transcription factors TLX1 and TLX3 with T-cell acute lymphoblastic leukemia, as well as HOXA11, PREX2, and RET with AML." (PMID 38769532, 2024). "In T-cell ALL, up to 22 different oncogenes have been identified as TCR translocation partners; the LMO2, TAL1, and TLX1 genes were most frequently involved in these rearrangements and the majority of all TCR translocations involved the TRD locus." (PMID 25515027, 2014). "T cell acute lymphoblastic leukemia (T-ALL) is a cancer of early thymocytes and is characterized by recurrent chromosomal rearrangements that activate oncogenic transcription factors such as TAL1/2, LMO1/2/3, NKX2.1/2.2, TLX1, TLX3, or HOXA." (PMID 35536646, 2022).
breast carcinoma (4 papers, 2017 to 2023). "The most co-enriched sets include MOHANKUMAR_TLX1_TARGETS_DN, genes down-regulated by TLX1 in a breast cancer cell line; POOLA_INVASIVE_BREAST_CANCER_UP, genes up-regulated in tissues from patients with vs. without breast cancer." (PMID 28583075, 2017). "A previous study had reported that some homeobox genes, such as HOXB13, TLX1, and HNF1B, were hypermethylated in the early stages of breast cancer." (PMID 32156290, 2020). "Although, to the best of our knowledge, TLX1 hypermethylation has not been previously associated with CRC, one study showed it is methylated in a high frequency of early stage breast cancers." (PMID 28351398, 2017).
asplenia (2 papers, 2022 to 2023). "Tlx1 deletion causes asplenia in mice, and deregulation of TLX1 expression is involved in the pathogenesis of congenital disease in human patients." (PMID 37298663, 2023). "We discover that a single amino acid mutation in the tlx1 transcription factor is most likely causal for the most drastic change, the loss of the spleen (termed “asplenia”) in seahorses." (PMID 36494371, 2022). "Our results strongly suggest that a seahorse-specific mutation in tlx1 leads to asplenia, as confirmed by CRISPR-Cas9 experiments." (PMID 36494371, 2022).
bladder cancer (2 papers, 2023). "This is the first study to show that BCAR4 and miR-644a can regulate the expression of TLX1 and the expression of TLX1 was associated with bladder cancer progression." (PMID 37627900, 2023). "On the other hand, the overexpression of TLX1 or the inhibition of miR-644a increased bladder cancer cell migration." (PMID 37627900, 2023).
breast tumor (2 papers, 2009 to 2021). "The expression level of HOXC12 is increased in breast tumor samples and TLX1 shows misregulation in cancer." (PMID 34470627, 2021). "To corroborate the DCIS-specific methylation profiles of TLX1, CGI 7:48, HOXB13, and HNF1B, we then extended the COBRA analysis to a series of primary breast tumors of different histological type and stage." (PMID 19250546, 2009).
colon cancer (2 papers, 2012 to 2023). "While GALR1 and TLX1 showed near perfect performance in classifying colon cancer (AUC of 0.97 for both), ZNF154 only achieved an AUC of 0.81 within this tumor type." (PMID 37835520, 2023).
acute leukemia (1 paper, 2011). A clonal (malignant) hematopoietic disorder with an acute onset, affecting the bone marrow and the peripheral blood. "Although TLX1 or NOTCH inhibitors may not be effective as single agents, they may still contribute to combination therapy for TLX1-driven acute leukemia." (PMID 21326611, 2011).
B-cell lymphomas (1 paper, 2014). "The oncogenic potential of TLX1 was demonstrated in IgHμ-TLX1Tg mice which develop mature B cell lymphoma after a long latency period, suggesting the requirement of additional mutations to initiate malignancy." (PMID 24586935, 2014). "Transgenic mice in which the TLX1 gene is placed under the control of the immunoglobulin heavy chain (IgH) promoter and enhancer, thus directing its expression predominantly to the B cell compartment (IgHμ-TLX1Tg mice), develop mature marginal zone B-cell lymphomas after an extended latency." (PMID 24586935, 2014).
diabetes (1 paper, 2017). "Furthermore, Tlx1 (Hox11)+ stem cells in the spleen effectively regenerated into insulin-producing islet cells in the pancreas of recipient mice, indicating that the spleen is a source of stem cells for the treatment of diabetes." (PMID 28135283, 2017).
Hereditary breast cancer (1 paper, 2025). Breast carcinoma that has developed in relatives of patients with history of breast carcinoma. "Some of this is explained by association with somatic genetic variants in genes TLX1 and CDH1; the latter is a known risk gene in hereditary diffuse gastric cancer and hereditary breast cancer, and it is tempting to speculate that NMD has a mediating role in this." (PMID 41023738, 2025).
liver cancer (1 paper, 2023). An epithelial or non-epithelial malignant neoplasm that arises from the liver. "Applying this technology on the sequenced plasma samples derived from patients with liver cancer or healthy controls, we found that ZNF154 and TLX1 performed with similar sensitivity (20% and 21%, respectively) when forcing the specificity to its maximum level (93% and 94%, respectively)." (PMID 37835520, 2023). "Importantly, ZNF154 enabled near-perfect classification of liver cancer samples with an AUC of 0.92, whereas GALR1 and TLX1 only produced AUC values of 0.64 and 0.77, respectively." (PMID 37835520, 2023).
lung carcinoma (1 paper, 2014). "TLX1::NFIC, MAX and Myc are predicted to have stronger binding affinity in those individuals with the risk allele, highlighting the potential functional role of this SNP in lung cancer." (PMID 24920305, 2014).
lymphoma (1 paper, 2011). A malignant (clonal) proliferation of B- lymphocytes or T- lymphocytes which involves the lymph nodes, bone marrow and/or extranodal sites. "To verify that doxycycline was inhibiting TLX1 expression and activity, we measured TLX1 and CCR7 levels by QPCR in the lymphomas of recipient mice." (PMID 21326611, 2011).
myeloid malignancies (1 paper, 2014). "That a proportion of mice developed myeloid malignancies was consistent with our previous report that expression of TLX1 in myeloid progenitors predisposed mice to myeloid hyperplasia." (PMID 24586935, 2014).
stomach cancer (1 paper, 2023). "By contrast, ZNF154 displayed the largest amount of differential methylation for stomach cancer (difference in median methylation 0.63), improving performance over TLX1 or GALR1 (difference in median beta value at 0.50 and 0.30, respectively)." (PMID 37835520, 2023).
T-cell leukemia (1 paper, 2019). A malignant disease of the T-lymphocytes in the bone marrow, thymus, and/or blood. "In murine HPCs, Tlx1/Hox11, an oncogenic transcription factor involved in human T-cell leukemia, transcriptionally regulates ALDH1A1 gene expression." (PMID 30733805, 2019).
uterine corpus endometrioid carcinoma (1 paper, 2023). "At probe cg14861089 in TLX1 (hg19/chr10:102,895,044), the difference in median beta values between tumor and normal samples across all 14 cancer types ranged from 0.03 in kidney renal clear cell carcinoma (KIRC) to 0.73 in uterine corpus endometrioid carcinoma (UCEC)." (PMID 37835520, 2023).
virus infections (1 paper, 2019). "However, adult Tlx1+ cells might still regain the potential to differentiate into mature splenic stromal cells under conditions of tissue repair when there is massive cell death of mature spleen stromal cells, e.g., after severe virus infections and inflammation." (PMID 31892733, 2019).
tumor (9 papers, 2011 to 2023). "Interestingly, PHF6 mutations are associated with tumours expressing the TLX1 and TLX3 oncogenes." (PMID 26103525, 2015). "The average beta value across all tumor-derived cell lines was very high: 0.87 for TLX1, 0.90 for GALR1, and 0.94 for ZNF154." (PMID 37835520, 2023). "Our study goes further to suggest that established TLX1 tumors have activated strong pathways that render the TLX1 gene set largely dispensable in the established tumor." (PMID 21326611, 2011). "We mined tumor methylation array data from the Cancer Genome Atlas (TCGA) covering 14 cancer types and identified two novel, broadly-occurring methylation markers at TLX1 and GALR1." (PMID 37835520, 2023). "Interestingly, the combination of ZNF154 with either TLX1 or GALR1 resulted in the successful detection of all tumor samples (100% sensitivity)." (PMID 37835520, 2023). "EYA4, TFPI2 and TLX1 were hypermethylated in more than 90% of all tumours examined." (PMID 28351398, 2017). "Suppression of TLX1 expression slowed the growth of TLX1 tumor cell lines." (PMID 21326611, 2011). "The biological pathways impacted by TLX1 have lost their importance in the established tumor." (PMID 21326611, 2011). "An advantage of our conditional mouse model is that it allowed us to investigate whether persistant TLX1 expression is required for tumor maintenance." (PMID 21326611, 2011). "The difference in median beta value between tumor and normal samples for colon was 0.13 for ZNF154, while TLX1 and GALR1 showed a difference of 0.70 and 0.60, respectively." (PMID 37835520, 2023). "However, at this concentration, the overlap between tumor and normal blood sample methylation signal from single probe methylation array data became so extensive that the maximum AUC value obtained was 0.57 (TLX1 combined with ZNF154 and the triple marker assay)." (PMID 37835520, 2023). "Considering each of the markers individually, ZNF154 reached 82% sensitivity, while TLX1 and GALR1 correctly classified 90% and 95% of the tumor samples, respectively." (PMID 37835520, 2023). "The assay with the highest correct classification of tumor samples was TLX1 combined with ZNF154 and the triple marker assay, both of which reached 79% sensitivity across all tumor samples." (PMID 37835520, 2023). "Here, we assessed methylation data for TLX1, GALR1, and ZNF154 in cell lines derived from non-tumor (n = 30) or tumor (n = 23) cell karyotypes, and in addition nine cell lines with no designation." (PMID 37835520, 2023). "These in vitro model systems reflect most of the different genetic subtypes of human T-ALL and included TLX1/3 positive (ALL-SIL, DND41 and HPB-ALL), TAL-R positive (PF-382, JURKAT and KE-37) and immature/HOXA overexpressing (LOUCY) tumor lines." (PMID 28801656, 2017). "A systems biology analysis of the regulatory circuit controlled by TLX1 and TLX3 in T-ALL found these factors as master regulators and identified the runt-related TF 1 (RUNX1) as a tumor suppressor." (PMID 25428367, 2014). "Thus, ZNF154, TLX1, and GALR1 methylation were elevated across the majority of tumor-derived cell lines." (PMID 37835520, 2023). "The tumors exhibited dependence on persistent NOTCH and TLX1 signaling; however, neither was absolutely essential for tumor growth." (PMID 21326611, 2011). "TLX1 showed high methylation (>0.4) in 18/23 tumor-derived cell lines and two non-tumor cell lines." (PMID 37835520, 2023). "Three genes, EYA4, TLX1 and TFPI2 are hypermethylated in >90% of all tumour samples, regardless of CIMP subtype." (PMID 28351398, 2017).
cancer (7 papers, 2010 to 2025). A tumor composed of atypical neoplastic, often pleomorphic cells that invade other tissues. "Functional classification of the TLX1/NOTCH-coregulated targets also showed enrichment for genes associated with other human cancers as well as those involved in developmental processes." (PMID 20618946, 2010). "Based on the evidence that LHX5 and TLX1 have the potential to promote neuronal differentiation, we speculated that they may also be linked to cancer stemness and recurrence of GBM." (PMID 34238116, 2021). "Compared to ZNF154 alone, the addition of TLX1 and GALR1 into a three-marker assay improved the AUC value by more than 0.07 in 4 cancer types." (PMID 37835520, 2023). "In this study we mined TCGA methylation data from 14 cancer types and identified two additional methylation markers for use in combinatorial testing: GALR1 and TLX1." (PMID 37835520, 2023). "To summarize each marker, we found the average of the sensitivity values in tissue samples across all 14 cancer types was 78% for GALR1, 81% for TLX1, and 84% for ZNF154." (PMID 37835520, 2023). "We identify two novel, multi-cancer markers in the intronic or promoter regions of TLX1 and GALR1, respectively, and report the benefit of combining them with ZNF154 as a multi-cancer assay." (PMID 37835520, 2023).
bacterial infection (1 paper, 2019). "In support of this possibility, we have previously demonstrated that LPS treatment, which mimics systemic bacterial infection, significantly enhances the level of Tlx1 expression in Tlx1+ cells." (PMID 31892733, 2019).
TLX1 also shares sentences with these, for which no sentence is quoted: lung adenocarcinoma (2 papers); Ectrodactyly (1); embryonal cell carcinoma (1); endometriosis (1); ependymoma (1); esophagus tumors (1); glioma (1); insulinoma (1); laryngeal carcinoma (1); prostate adenocarcinoma (1); T-cell lymphoma (1).